ACOT13 (acyl-CoA thioesterase 13)
Description:
Catalyzes the hydrolysis of acyl-CoAs into free fatty acids and coenzyme A (CoASH), regulating their respective intracellular levels. Has acyl-CoA thioesterase activity towards medium (C12) and long-chain (C18) fatty acyl-CoA substrates (By similarity). Can also hydrolyze 3-hydroxyphenylacetyl-CoA and 3,4-dihydroxyphenylacetyl-CoA (in vitro) (By similarity). May play a role in controlling adaptive thermogenesis (By similarity).
Synonyms: THEM2; HT012; PNAS-27
Tractability: Small molecule: a structure with a bound ligand is known; it has a binding pocket of medium quality. PROTAC: ubiquitination databases record sites on it; its protein half-life has been measured.
Target class: Enzyme; Hydrolase
Gene: Protein-coding gene on chromosome 6 (24,666,921 to 24,705,065, forward strand). Ensembl gene ENSG00000112304.
Subcellular location: Cytoplasm, cytosol; Mitochondrion; Nucleus; Cytoplasm, cytoskeleton, spindle
Subcellular location (Human Protein Atlas): Cell Junctions
Pathways (Reactome):
Metabolism: Mitochondrial Fatty Acid Beta-Oxidation
Gene Ontology:
Molecular function: fatty acyl-CoA hydrolase activity; protein binding; long-chain fatty acyl-CoA hydrolase activity; medium-chain fatty acyl-CoA hydrolase activity; short-chain fatty acyl-CoA hydrolase activity
Biological process: protein homotetramerization; negative regulation of cold-induced thermogenesis
Cellular component: mitochondrion; nucleus; cytosol; cytoplasm; mitochondrial matrix; spindle
Genetic constraint (gnomAD): Loss-of-function variants: 10 observed, 11.64 expected, observed/expected ratio (o/e) 0.86, 90% interval 0.53 to 1.45. The upper end of that interval is the gene's LOEUF score, 1.45, which puts it in group 6 of 6, group 1 being the genes least tolerant of losing a copy. Missense variants: 172 observed, 183.73 expected, observed/expected ratio (o/e) 0.94, 90% interval 0.83 to 1.06. Synonymous variants: 53 observed, 63.94 expected, observed/expected ratio (o/e) 0.83, 90% interval 0.66 to 1.04.
Homologues: Orthologues: chimpanzee ACOT13 (99% identical), macaque ACOT13 (91% identical), mouse Acot13 (84% identical), guinea pig ACOT13 (79% identical), pig ACOT13 (79% identical), dog ACOT13 (78% identical), rat Acot13 (76% identical), tropical clawed frog acot13 (69% identical), zebrafish acot13 (69% identical), Drosophila melanogaster CG16986 (36% identical), Drosophila melanogaster CG16985 (36% identical).
Diseases named in the same sentence as ACOT13 in open-access papers:
ACOT13 is named in the same sentence as 23 diseases in open-access papers, as found by Europe PMC text mining. Sharing a sentence is not in itself a finding about the gene and the disease. The quoted sentences say what the papers report.
Insulin resistance (2 papers, 2022 to 2024). Increased resistance towards insulin, that is, diminished effectiveness of insulin in reducing blood glucose levels. "In this regard, blocking the inhibitory effect of PCTP/ACOT13 and leucine might enable insulin to suppress PPARa activity for longer and avoid insulin resistance." (PMID 35269927, 2022).
Obesity (2 papers, 2015 to 2024). Accumulation of substantial excess body fat. "The loss of Acot7, Acot11/Them1, Acot13/Them2, and Acot15/Them5 result in phenotypes ranging from increased neurodegeneration to altered susceptibility to high-fat diet induced obesity, fatty liver, and insulin resistance through unknown mechanisms that unexpectedly altered whole body metabolism." (PMID 25760036, 2015).
ovarian serous cystadenocarcinoma (2 papers, 2023 to 2024). A malignant serous cystic epithelial neoplasm arising from the ovary. "This research aimed at evaluating the expression and prognostic value of ACOT13 in ovarian serous cystadenocarcinoma (OSC)." (PMID 37424730, 2023).
bladder cancer (1 paper, 2022). "We obtained the results of immunohistochemical staining of ACOT13, CYP1, DECR1, IL4I1, and SCD in both normal tissues and bladder cancer tissues and found that the expression of CYP1 was higher in normal tissues, while other genes were higher in tumor tissues than in normal tissues." (PMID 36131793, 2022).
Hepatitis (1 paper, 2019). Inflammation of the liver. "Although a clustering of associations for hepatic activity and lipid metabolism was absent, the acyl-CoA thioesterase 13 (ACOT13) expression and periportal or periseptal interface hepatitis revealed a significant negative association." (PMID 31819046, 2019).
non-small cell lung carcinoma (1 paper, 2023). A group of at least three distinct histological types of lung cancer, including non-small cell squamous cell carcinoma, adenocarcinoma, and large cell carcinoma. "For example, the recent association of a MER4 retroelement on Chr6 p22.3 with the outcome of check-point blockade in non-small cell lung cancer is likely due to incomplete removal of the first intron of ACOT13 locus where this retroelement resides." (PMID 37502711, 2023).
ovarian carcinoma (1 paper, 2023). A malignant neoplasm originating from the surface ovarian epithelium. "First, additional in vivo and in vitro studies are required to clarify the mechanism of ACOT13 in the occurrence of ovarian cancer, and this is where we will work in the future." (PMID 37424730, 2023).
tumor (5 papers, 2017 to 2024). "We found that ACOT13 protein was mainly localized in the cytoplasm, with low expression in normal ovarian tissue and medium to high intensity staining in tumor tissue." (PMID 37424730, 2023). "This suggested that ACOT13 exerts a great effect on tumor formation and immune invasion." (PMID 37424730, 2023). "Besides, the expression of ACOT13 was correlated with tumor stage, and the expression level of ACOT13 was higher in stages I-II (G1) than in stages III-IV (G2)." (PMID 37424730, 2023). "This research firstly shows the high expression of ACOT13 in OSC and correlated with tumor staging." (PMID 37424730, 2023).
cancer (3 papers, 2017 to 2025). A tumor composed of atypical neoplastic, often pleomorphic cells that invade other tissues. "Analysis of pan-cancer data showed that ACOT13 also has disease prognostic potential in kidney chromophobe (KICH) and kidney renal clear cell carcinoma (KIRC)." (PMID 37424730, 2023).
ACOT13 also shares sentences with these, for which no sentence is quoted: autosomal dominant polycystic kidney disease (2 papers); breast carcinoma (1); dyslexia (1); Glucose intolerance (1); hepatic carcinoma (1); Hepatic steatosis (1); kidney disease (1); liver disease (1); osteosarcoma (1); overnutrition (1); pancreatic cancers (1); reproductive system tumors (1); steatosis (1); testis cancer (1).